CD34 (CD34 molecule)
Diseases named in the same sentence as CD34 in open-access papers (continued):
Sharing a sentence is not in itself a finding about the gene and the disease.
tumor (continued). "The combination of RY103 and sunitinib significantly downregulated the protein expressions of CD34 and ATF4, indicating an effective blockage of the GCN2 pathway and thus suppression of tumor angiogenesis." (PMID 39065567, 2024). "Immunofluorescence analysis showed increased MVD with increased CD34 and CD31 expression in overexpressed GP73 tumor-bearing tissues." (PMID 38939041, 2024). "CD34, CD31, and vWF are commonly used vascular marker proteins, and immunohistochemical (IHC) staining of these proteins can detect vascular formation in tumor tissues." (PMID 39230586, 2024). "The findings revealed that treatment with hemagglutinine resulted in downregulation of CD34, Ki67, EGFR, Bcl-2, and VEGF expressions in tumor tissues while up-regulating the pro-apoptotic protein Bax expression." (PMID 38751791, 2024). "Immunohistochemical examinations showed that the tumor cells were positive for ERG, CD34, CD31, and vimentin, whereas CK (AE1/AE3), EMA, CK7, HMB45, SMA, CD117, Dog-1, and S-100 were negative; Ki-67 labeling index was 30%." (PMID 39465747, 2024). "The relevance of prognostic biochemical, histological, and imaging parameters, such as IGF-2 levels, vimentin, CD34, bcl-2, or CD99 positivity but cytokeratin negativity, and tumor size > 10 cm, is unclear." (PMID 39138498, 2024). "In IDO1-SOE mice, serum KP activity and VEGFA concentration were increased accompanied by a rise in the expression of CD34, ATF4, IDO1, and VEGFA in tumor tissues, with the most significant uplift observed in ATF4 and IDO1 expression." (PMID 39065567, 2024). "Further bioinformatics analysis of miR-24-1-5p targets, including CD34, ACACA, TPM3, UFC1, EDIL3, and CHEK1, reinforces their role in tumor immune cell infiltration and the transformation of the tumor microenvironment." (PMID 38840234, 2024). "In newly formed vessels within the tumor stroma, most endothelial cells are CD31 and CD34 immunopositive and co-express VEGF." (PMID 39684754, 2024). "Accordingly, tolvaptan significantly reduced vascularization in tumor masses, as supported by the lower expression levels of VEGF and CD34 in tumors excised from tolvaptan-treated animals." (PMID 39125971, 2024). "Nuclear fission is easy to see.Immunohistochemical results show that the tumor cells diffusely express Nestin, a-SMA, SDHB, a small amount of CD34, and CD117, DOG-1, Calponin, h-Caldesmon, Desmin, S-100 and pan-cytokeratin (CKpan) are all negative." (PMID 38388419, 2024). "Nevertheless, the microvessel density (MVD) in tumor tissues was assessed by IHC assays using antibodies to CD31 and CD34 in order to clarify the effect of Exo-SR and circUPF2 on tumor angiogenesis in vivo." (PMID 38811968, 2024). "Tumor cells can express various vascular endothelial antigens, including CD31, CD34, ERG, and calponin." (PMID 38962269, 2024). "We next analyzed the frequency of Lin-CD34+DNAM-1brightCXCR4+cells recovered in blood, tumor and uninvolved tissue samples in order to provide an estimate of their tissue trafficking." (PMID 38390333, 2024). "Focusing on CAFs, our analysis revealed a novel subpopulation marked by CD34+PI16+, which gave rise to the classical ACTA2+MCAM+ CAFs in tumor, also known as myCAF (data unpublished)." (PMID 39401181, 2024). "Among ALK gene fusion-related neoplasms, SAMS is a recently reported tumor distinguished by the existence of myxoid spindle cell whorls and cords with co-expression of ALK, CD34, and S100 proteins." (PMID 39202049, 2024). "The aim of this study was to determine the relationship between POSTN expression (in tumor cells [NSCLC cells] and the tumor stroma) and pro-angiogenic factors (CD31, CD34, CD105, and VEGF-A) and microvascular density (MVD) in NSCLC." (PMID 39272978, 2024). "The hypermethylated pattern identified in the promoters of EC markers CD34, EMCN, and TEK suggests a downregulated expression in tumor tissues." (PMID 39103878, 2024).
tumor (continued). "T-cell subsets in the tumor-sparse region also showed higher relative abundance of fibronectin, SMA and CD34, which are markers of neovascularization and angiogenesis." (PMID 39001353, 2024). "This tumor sample showed positive immunoreactivity for STAT6 and CD34, while EMA was poorly expressed." (PMID 38341593, 2024). "In the same study, Masson's tumor stained with immunohistochemical markers such as CD31, CD34, actin, and the relevant gene specific to erythroblast transformation led to an awareness of the differential diagnosis." (PMID 39559677, 2024). "We compared the immunohistochemical expression of CD34, VASH1, and carbonic anhydrase 9 (CA9) between patients who achieved tumor clearance at operation (ypT0) and those with residual disease after cystectomy." (PMID 38376711, 2024). "CD34/PAS staining showed that after BMP2 knockdown, the number of formed VMs within the tumor was significantly decreased." (PMID 38610001, 2024). "IHC staining for vimentin and synaptophysin was positive, CD34 and EMA showed very focal positivity in the tumor cells, while SMARCB1 (INI-1) was retained." (PMID 38265099, 2024). "The multivariate Cox proportional regression model identified significant predictors as independent prognostic factors for OS: CCL17-T high, CD34 high, CCR4 + CD73 + ≥ 13, CCR4-T high, CD73-T high, HHLA2, MVI, Treg/CD8 ≥ 1, and tumor size ≥ 5 cm." (PMID 38914802, 2024). "The mainly positive rates of immunohistochemical staining for various tumor markers were 97.2% (35/36) for HMB-45, 97.1% (34/35) for Melan-A, 88.5% (23/26) for SMA, and 86.7%(26/30) for CD34." (PMID 39220650, 2024). "Immunohistochemically, the tumor cells are diffusely positive for vimentin and focally positive for CD68 and CD34." (PMID 38256198, 2024). "The tumor cells stain strongly for endothelial markers such as CD31, CD34, and ERG, and can stain positive for neuron-specific enolase and S-100 as well." (PMID 39252750, 2024). "We performed triple immunostaining for α‐SMA, CD34, and IL32 on tumor sections to quantify the percentage of pericyte‐IL32 positive blood vessels in each patient, indicating that IL32 was expressed in PCs." (PMID 39435643, 2024). "We found that most of the CD34 and CD105 expressed in the peritumoral tissue represented new tumor vessels after TACE treatment; these factors were barely expressed in the intratumoral region in the experimental group." (PMID 36925931, 2023). "Immunohistochemically (IHC), tumor cells were positive for SMA, MDM2, and p16; the cells were negative for desmin, MyoD1, Myogenin, pan-cytokeratin, S100, SOX10, HMB45, Malen-A, CD34, CD31, CD99, and ALK." (PMID 37735390, 2023). "The post-operative pathologicalimmunohistology showed the tumor to be a Ki-67 < 1%, SDHB+, SMA+, CD34+, CD117+, DOG-1+,and Desmin+ GIST with tumor regression grade 2 and negative margins." (PMID 36632625, 2023). "Absence of CD34 and/or CD31 in vascular structures was the most common indicator of VM, while expression of CD34 and/or CD31, in addition to various other endothelial, stem cell or tumour cell markers, indicated tumour to endothelial transdifferentiation." (PMID 36823554, 2023). "All the markers—CD31, CD34, and CD105—were shown as highly expressed within vessels with abnormal morphology, which further confirms the role of these molecules in tumor pathological growth." (PMID 37296922, 2023). "The colocalization of CD34 (a telocyte marker) with AmotL2, FKBP51, and IQGAP1 in tumor vessels was indicative of a role for these three scaffold proteins in tumor angiogenesis and vascular invasion." (PMID 37415743, 2023). "We next applied IHC serial section analysis with anti-CD34, -CD31, CD146, or -GFP antibodies, respectively, revealing relations of tumor or blood vessels and GFP+ Mc38 cells on varied-sized metastases." (PMID 36781833, 2023).
tumor (continued). "Tumor microenvironment including stroma/collagen (α-SMA and trichrome staining) and vascular endothelial cells (CD34) was preserved in ex vivo tissue slice culture over 5 days." (PMID 37713330, 2023). "Despite the absence of studies considering tumor budding and angiogenesis, several authors have evaluated MVD (through immunostaining for CD34 and CD105) and clinical-pathological parameters of tumor aggressiveness." (PMID 36565216, 2023). "KIT, CD34, THY1, and EPCAM were expressed in large vessel structures and tumor capsules from patients #4001 and #3559." (PMID 37932266, 2023). "In the tumor compartment, patients with PR had higher expression of ER-alpha, PD-L1, Pan-AKT, CD68, Ki-67, and Fibronectin, but lower expression of CD44, CD127, CD34, and VISTA." (PMID 37153589, 2023). "Whilst the majority of LSC are enriched within the CD34+ compartment, up to ~ 25% of AML cases are CD34‐, and LSC activity can be demonstrated for these tumours." (PMID 37872885, 2023). "Histopathological investigations confirmed that the tumor was HBL with common characteristics and immunostaining of inhibin alpha, and endothelial cell markers, CD31, CD34, and CD56, also confirmed the present case as HBL." (PMID 37273678, 2023). "As biomarkers for the tumor microenvironment (TME), CD163 and CD68 (tumor-infiltrating macrophages—TAM), as well as CD34 and CD105 (intratumoral microvascular density—IMVD), were chosen." (PMID 37296922, 2023). "Nevertheless, in samples with high-intensity tumor budding, the MVD assessed by CD34 immunostaining was higher in the budding area than in the area outside the budding." (PMID 36565216, 2023). "The tumor was positive for CD31, CD34, D2-40, CD68, Ki-67 (1% to 2% positive nuclear staining) immunomarkers as well for the smooth muscle markers SMA and desmine." (PMID 37297823, 2023). "Strikingly, when analyzing the immunophenotype of tumor cells within this cluster, an upward trend in the expression levels of CD19, CD34, CD24, CD20, nuTdT, cyMPO, and CD33 was recorded." (PMID 38250553, 2023). "Herein, we showed that miR-181a inhibition enhanced the growth of NBM CD34+ cells and that this effect was enhanced by BCR-ABL, which strongly suggested the tumor-suppressor role of miR-181a in BCR-ABL+ leukemic cells." (PMID 38103082, 2023). "One hundred and fifty samples of OSCC were subjected to immunohistochemistry to assess the intensity of tumor budding (by immunostaining for multi-cytokeratin) and MVD (by immunostaining for CD34 and CD105, independently)." (PMID 36565216, 2023). "In immunohistochemical study, the tumor cells were positively stained with CD31 and CD34 whereas they were negatively stained with TFE3, SMA, S-100, HHV-8 and EMA." (PMID 34757619, 2023). "Vessels with an endothelial cell lining were CD34+ with a PAS+ vascular basement membrane and accounted for the majority of the vasculature in all tumour sections." (PMID 37568738, 2023). "In an immunohistochemistry study, the tumor cells were diffusely immunoreactive for CD117, CD34, and DOG1." (PMID 37228978, 2023). "We found that, while GFP+ Mc38 cells just began to colonize; some CD34+ staining showed even before tumor cells arrived (the 2nd columns: CD34+ vs. GFP+ staining); later an intensive CD34+ staining almost overlapped with that of GFP+ on bigger metastases." (PMID 36781833, 2023). "Indeed, the exposure of CD34+ precursors of pDCs and of differentiated pDCs to soluble tumor components could respectively block their differentiation or induce their apoptosis and be at the origin of the decrease in the proportions of pDCs in circulation and in the metastases of patients." (PMID 37190135, 2023). "We next proved that in vitro co-culture of the ex vivo F4/80+TAMs with the endothelial cells (SVEC4–10) under tumor-cell conditioned media (TCM) greatly stimulated the expression of a few key angiogenic markers including CD31, CD34, TIE2, VEGFA, Ki67, etc.." (PMID 36781833, 2023).
tumor (continued). "Using healthy donor CD34+ cells as a reference, we detected overexpression of DGKA, DGKG, DGKD and DGKQ in tumor samples, while DGKH and DGKZ were unchanged." (PMID 37509516, 2023). "In our study, in tumors with high-intensity tumor budding, the MVD (assessed by CD34 immunostaining) was higher in the budding area than in the area outside the budding." (PMID 36565216, 2023). "Tumor cells express positivity with endothelial markers such as CD31, CD34, ERG, and von Willebrand factor (VWF)." (PMID 34757619, 2023). "From an angiogenic standpoint, CD31, CD34, CD105, and VEGF are widely used to characterize MVD in the field of tumor research." (PMID 36925931, 2023). "Tumor cells in the epithelial and mesenchymal regions DOG-1, CD34, S-100, SOX-10, STAT 6, SMA, desmin, Syn, and CgA were negative; SDHB-positive expression; Ki-67 proliferation index was 3%." (PMID 37658451, 2023). "highlights six genes (VEGFA, KDR, ESM1, CD34, PECAM1, and ANGPTL4), but only four of them were expressed by endothelial cells while VEGFA and ANGPTL4 were mainly expressed by tumor cells." (PMID 36423636, 2022). "In addition, chemotherapeutic regimens, especially cyclophosphamide, are commonly used in combination with growth factors for autologous HSCs mobilization, which could improve CD34+ cells yield and reduce tumor cells burden, but with the expense of increased toxicity." (PMID 35317856, 2022). "To evaluate the alloreactive effect of T cells differentiated from allogeneic CD34 + stem cells on tumour growth, we compared the antitumour efficacy of ERY974 against PC10 and NCI-H446 in huNOG mice administered CD34 + stem cells from different donors." (PMID 36071036, 2022). "To better understand the correlation between TFPI2 expression and tumour angiogenesis, we divided these samples into three groups based on TFPI2 amount, as defined by expression scores, and studied the CD34-MVD among these three groups." (PMID 35501390, 2022). "Studies reported in the literature have used mouse models generated from human CD34+ cells and PBMC sources to evaluate tumor-immune responses with different immunotherapeutic agents." (PMID 36212401, 2022). "In the paper, we explored the expression condition of tumor neovascular EC markers CD31, CD34, and CD105 in GGNs by the IHC method, analyzing the difference of MVD in GGNs with different vascular manifestations under CT imaging." (PMID 36185269, 2022). "For determining vascular and pericyte density in tumor tissue, immunohistochemical analysis was performed with CD31, alpha-smooth muscle actin, and CD34 antibodies." (PMID 36422502, 2022). "CD31/CD34 and CD8/PD-L1 comparisons revealed similar profiles between multisite 3D fusion and in toto tumor samples (p = 0.03), whereas discordances in standard sampling (p = 0.05)." (PMID 35629151, 2022). "The tumor cells were also diffusely positive for DOG-1 (10/10, 100%) and displayed focal to diffuse positivity for CD34 (11/12, 92%)." (PMID 35885469, 2022). "Administration of the well-known OXPHOS inhibitor metformin eradicated CML stem/progenitor cells and re-sensitized CD34+ CML cells to imatinib in vitro and in patient-derived tumor xenograft murine model." (PMID 35444236, 2022). "Expression of VEGFC and PGF was highly correlated with the expression of endothelial markers in tumor samples, including CD31, CD34, and ENG (endoglin, a co-receptor for TGFβ)." (PMID 35600354, 2022). "In case of CD34-negative tumor microenvironment, the effect of NT5DC2 expression on survival was not apparent anymore (CD34+ environment: Log Rank p < 0.001, CD34- environment Log Rank p = 0.442)." (PMID 35326547, 2022).
tumor (continued). "Immunostaining showed tumor cells to be positive for at least one of the vascular markers, that is, CD31, CD34, factor VIII-related antigen or Ulex europaeus agglutinin-1, while negative for epithelial cell membrane antigen." (PMID 36083389, 2022). "In immunohistological studies, the tumor tissue totally expressed CD20+, the vascular endothelium was brightly stained in reaction to CD34+ and expressed extremely weakly VEGF." (PMID 35510125, 2022). "This intra-tumor heterogeneity was evident especially when looking at the expression of some markers such as CD49c (integrin α3), CD61 (integrin β3), and CD34, which were restricted to distinct subclones." (PMID 36568177, 2022). "The authors observed that in PCa, a sensitive biomarker for newly derived blood vessels was CD34, and IHC analysis and MVD quantification within the tumor represents the basis for understanding the effects of antiangiogenic treatment." (PMID 35884977, 2022). "The knockdown of linc00958 inhibited RSF-1 and Ki67, curbing tumor growth; it also inhibited VEGFA and CD34, decreasing angiogenesis in mice." (PMID 36056431, 2022). "Tumor volume as well as the expression of angiogenic factors CD31, CD34, IB4 and VEGF were significantly elevated in CD204−/− mice in comparison with CD204+/+ mice in glioma model." (PMID 36686729, 2022). "With the aim of the timely diagnosis of such a form of tumor escape, our approach includes the obligatory examination of CD45, CD38, CD34 and CD24 expression vs. side-scatter (SSC) to find any suspicious cell populations among all nucleated cells." (PMID 36358863, 2022). "Immunohistochemistry staining (magnification, ×400) showed that the tumor cells were positive for STAT6, CD34, Ki67 (10%), CD99, Bcl2, and Vimentin." (PMID 36386546, 2022). "As it is well known, the expression of SFT markers STAT6, CD34, CD99 and bcl-2 can be lost in most aggressive tumours, following a process of dedifferentiation." (PMID 35864381, 2022). "In vivo experiments, miR-130a inhibition effectively suppressed the tumor growth by reducing the expression of angiogenic markers and the percentage of CD31+ and CD34+ to inhibit angiogenesis." (PMID 36338963, 2022). "By immunohistochemistry, DAM is typically a desmin-positive myofibroblastic tumour with variable expression of HMGA2, α-smooth-muscle actin (from 27% to 95% of cases) and CD34 (from 17% to 50%)." (PMID 35204448, 2022). "Here, previously the presence of CD34+ CAFs has been shown to be a marker of improved survival, and SMA+ CAFs were indicative for more advanced tumor stages." (PMID 35326547, 2022). "By Ki67 and CD34 staining, the TPVE with IPN hydrogel suppressed tumor proliferation and angiogenesis." (PMID 33685316, 2021). "According to a previous report, we transplanted Lin-CD34+ UCB cells into human IL-6-Tg NOG mice, which generates TAMs with a functionally immunosuppressive nature and show an enhanced tumor-growth." (PMID 33692791, 2021). "Myc inhibitor 10058-F4 suppressed CIP2A in 80% of CD34+ cells (p = 0.04) and 85% of K562 cells (p = 0.01), preventing Myc/MAX interaction and restoring tumour-suppressor functions in vitro K562 and CD34+ cell lines." (PMID 33440869, 2021). "Immunohistochemistry revealed that the tumor was S-100(+), SOX10(−), CD34(+), SMA(partially+), DOG-1(+), CD117(+), KI-67 (positive for 20% + of the subjects and 40% + of the hotspots), and SDHB(−)." (PMID 33879132, 2021). "Compared with the LY group, the expression of PCNA, CD34 and PATK in the transplanted tumor tissues of the P + LY group was down-regulated, and the difference was statistically significant (F = 0.000)." (PMID 34323647, 2021). "Immunohistochemical results exhibited that the CD31, CD34, F-VIII, FLI-1, and ERG were positive in tumor cells." (PMID 34032697, 2021). "We examined protein expression in B, T, and PDX samples for CCND1, KI67, CD34, GPC3, YAP, and EZH2 to provide loose validation of different tumor clusters." (PMID 34497364, 2021).